ACE (angiotensin I converting enzyme)
Diseases named in the same sentence as ACE in open-access papers (continued):
Sharing a sentence is not in itself a finding about the gene and the disease.
Hypertension (continued). "The Japanese Society of Hypertension recommends the use of angiotensin-converting enzyme inhibitors (ACE inhibitors) and angiotensin receptor blockers (ARBs), which enhance insulin sensitivity, for patients with diabetes and hypertension." (PMID 27437997, 2016). "Food protein hydrolysates are known to exhibit angiotensin converting enzyme (ACE) inhibitory properties and can be used as a novel functional food for prevention of hypertension." (PMID 27706040, 2016). "In a classical RAS, angiotensin (Ang) II produced from Ang I by an angiotensin-converting enzyme (ACE) is a strong bioactive substance and its activation contributes to the development of the hypertension." (PMID 26881037, 2016). "Angiotensin-converting-enzyme (ACE)-inhibitors are one of the most commonly used types of antihypertensives, and they are included in treatment guidelines for hypertension in Europe as well as the United States." (PMID 27192203, 2016). "In the CAD-Tgroup, however, the use of beta-blockers and angiotensin-converting enzyme (ACE)inhibitors, dyslipidemia, and hypertension accounted for 65% of the variance in 0V%(p<0.05)." (PMID 26647745, 2015). "Moreover, salt reduction is recommended in the treatment of hypertension because it produces not only a blood pressure lowering effect per se but also contributes to the antihypertensive effects of drugs and enhances the renal protective effect of angiotensin-converting enzyme (ACE) inhibitors." (PMID 26495970, 2015). "Development of angiotensin I-converting enzyme (ACE, EC 3.4.15.1) inhibitory peptides from food protein is under extensive research as alternative for the prevention of hypertension." (PMID 25768442, 2015). "Those participants with hypertension were significantly older, with higher BMIs, greater MABP, were more likely to have IHD and CKD, and use ACE inhibitors, aspirin, beta-blockers, calcium channel blockers, diuretics, and statins (P < 0.001)." (PMID 26327531, 2015). "This fact is well supported by the success of angiotensin converting enzyme (ACE) inhibitors and angiotensin receptor blockers (ARBs) as first line therapies in the treatment of hypertension and kidney disease patients." (PMID 26064882, 2015). "Captopril, the first oral angiotensin-converting enzyme (ACE) inhibitor, was isolated from Bothrops jararaca and is currently used commercially for the treatment of hypertension." (PMID 25811661, 2015). "Recently, most researches have been focused on the interactions between the ACE/Ang II/AT1R axis and miRNAs in hypertension." (PMID 25815211, 2015). "An ACE inhibitor or ARB should be given to patients with an ACS, especially in patients with an anterior myocardial infarction if hypertension persists, if there is an decreased left ventricular ejection fraction (LVEF), or if diabetes mellitus is present." (PMID 26718096, 2015). "Genes associated with renin-angiotensin-aldosterone system, such as angiotensinogen (AGT), angiotensin converting enzyme (ACE) and angiotensin II receptor 1 (AGTR1), were the most extensively studied as hypertension candidate genes." (PMID 25313554, 2014). "Current therapies for human hypertension include angiotensin II (Ang II) type 1 receptor (AT1R) inhibitors, angiotensin converting enzyme (ACE) inhibitors, diuretics, calcium channel antagonists, and β-blockers." (PMID 25136585, 2014). "Angiotensin-converting enzyme (ACE) inhibitors and angiotensin II receptor blockers (ARBs) are frequently prescribed for the treatment of hypertension." (PMID 24827148, 2014). "DHSGT showed potent inhibitory activity against ACE in vitro, with an IC50 value of 0.56 mg/ml, and it decreased the high blood pressure induced by increasing dietary fat in the HFD mouse group." (PMID 25280587, 2014). "Angiotensin I-converting enzyme (ACE) plays an important role in regulating blood pressure and hypertension." (PMID 24224169, 2013).
Hypertension (continued). "Angiotensin converting enzyme (ACE) is an important enzyme of RAAS and a drug target for treating patients with hypertension." (PMID 23666006, 2013). "In the current study, both ACE inhibitors and ARBs were found to be unassociated with NOD in patients with hypertension." (PMID 23509704, 2013). "Calcium channel blockers (CCBs), angiotensin receptor blockers (ARBs), angiotensin converting enzyme (ACE) inhibitors, and diuretics are generally used for hypertension therapy." (PMID 23634320, 2013). "The angiotensin receptor II blockers (ARBs) have been shown to be an effective treatment for hypertension in patients with CHD and HF in patients who are intolerant to ACE inhibitors." (PMID 23476746, 2013). "In essential hypertension, the activation of the renin–angiotensin–aldosterone (RAS) system plays a pivotal role and angiotensin-converting enzyme (ACE) inhibitors or angiotensin receptor blockers (ARBs) are commonly used for treatment." (PMID 23203441, 2013). "The major classes of antihypertensive agents, including angiotensin-converting enzyme (ACE) inhibitors, beta blockers, and calcium channel blockers, have been used to treat TKI-induced hypertension." (PMID 22327313, 2012). "The use of ARBs and/or angiotensin converting enzyme (ACE) inhibitors, alone or in combination with a calcium channel blocker or with a thiazide diuretic, has become the cornerstone of hypertension management." (PMID 22844584, 2012). "Finally the practical consequence of this study is that the 90 kDa ACE was associated with the presence of hypertension and the absence of this was associated with subjects with normal blood pressure levels, so this isoform would be a urinary marker of hypertension in normotensive subjects." (PMID 22666552, 2012). "In this study we investigated the effect of a nine-month treatment with the ACE inhibitor perindopril on PWV and the role of ET-1 in black hypertensive patients." (PMID 22914998, 2012). "Further adjustment for ACE inhibitor and angiotensin receptor blocker treatment did not substantially modify the association of hyperhomocysteinemia with albuminuria (OR = 2.18, 95%CI: 1.57-3.04), while decreasing the association of hypertension with albuminuria (OR = 1.39; 95%CI: 0.99-1.96)." (PMID 21943240, 2011). "Ramipril is a prodrug and is converted to the active metabolite ramiprilat by liver esterase enzymes, and is an angiotensin-converting enzyme (ACE) inhibitor, used to treat hypertension and congestive heart failure." (PMID 21731352, 2011). "Here, we studied the effect of cyclosporine on HNF4α and various RAS components to better understand cyclosporine induced hypertension and proposed HNF4α dysfunction and subsequent regulation of AGTR1, ACE, and ACE2 as a molecular rational." (PMID 21298017, 2011). "A number of studies have shown ACE inhibitors and ARBs to reduce ADMA levels in people with hypertension, diabetes mellitus and cardiac syndrome X." (PMID 21532773, 2010). "ACE inhibitors and AGTR1-blocking drugs are already extensively exploited as therapy for hypertension." (PMID 20886000, 2010). "Angiotensin converting enzyme (ACE) inhibitors and angiotensin 2 receptor blockers (ARBs) improve endothelial function and NO availability in conditions like CAD, hypertension and diabetes." (PMID 21532773, 2010). "The role of ACE inhibitory activity of IPP and VPP, and their effects on hypertension related biochemical markers, were also studied." (PMID 20721338, 2010). "It has been suggested that the equivocal results may be because ACE polymorphisms play a secondary rather than primary role in hypertension, or is due to BP being expressed dichotomously (hypertension vs. normotensive) rather than as a continuous quantitative trait." (PMID 19291311, 2009). "On the other hand, these differences disappear for ACE inhibitors/ARB and beta-blockers when adjusted for diagnosis, probably because hypertension is more common in women and these drugs are widely used for its treatment." (PMID 18973693, 2008).
Hypertension (continued). "The agents most often used for hypertension today include angiotensin receptor blockers (ARB) and angiotensin converting enzyme (ACE) inhibitors, which are both considered to improve glucose metabolism." (PMID 17903269, 2007). "After adjusting for age, gender, use of ACE inhibitor or ARB, use of a β-blocker, presence of hypertension, and baseline MLHF, intervention patients were less likely to have the outcome (IRR = 0.53; 95% CI 0.32, 0.89)." (PMID 16533388, 2006). "Genes encoding components of RAS, including angiotensinogen (AGT), angiotensin-converting enzyme (ACE), angiotensinogen II type-1 receptor (AGTR1), and renin, have been extensively investigated as genetic determinants of essential hypertension." (PMID 15642127, 2005). "Chromosome 17 contains the angiotensin-I converting enzyme (ACE) gene and there is good supporting evidence that this gene is involved in hypertension." (PMID 14975086, 2003). "In non-obstructive phenotypes with preserved blood pressure, hypertension can be managed with standard antihypertensives, including ACE inhibitors, ARBs and diuretics, especially when diastolic dysfunction is advanced and blood pressure control is paramount." (PMID 41590217, 2025). "Angiotensin-converting enzyme (ACE) inhibitors are known to regulate blood pressure by modulating vasoconstriction, and hence may also play a role in treating hypertension." (PMID 40076447, 2025). "Although other subgroups, such as those with hypertension or on ACE inhibitors and beta blockers, consistently showed non-significant trends, higher ORs in the VDD group suggest a pervasive impact of VDD on cardiovascular outcomes." (PMID 40362848, 2025). "In addition, hypertension is independently and highly prevalent among PWH, so the use of AT1R blockers (e.g., losartan) and angiotensin‐converting enzyme (ACE) inhibitors (e.g., enalapril) is common among this population." (PMID 40421794, 2025). "Brain volume measurements, ACE I/D genotypes, and APOEε4 status of the patients with or without hypertension." (PMID 40372199, 2025). "The search strategy combined Medical Subject Headings (MeSH) and free-text terms: “renin inhibitors”, “direct renin blockade”, “aliskiren”, “angiotensin-converting enzyme inhibitors”, “ACE inhibitors”, “angiotensin receptor blockers”, “ARB”, and “hypertension”." (PMID 41409925, 2025). "Dipeptides containing alanine from dry cured ham have been reported to have the ability to inhibit angiotensin-converting enzyme (ACE) and dipeptidyl peptidase IV (DPP IV), making them potential candidates for anti-hypertension and anti-hyperglycemic therapeutic agents, respectively." (PMID 41585459, 2025). "This study demonstrated that protein hydrolysates derived from Bambara groundnut (Vigna subterranea) contained peptides with dual inhibitory activities against ACE and DPP-IV, suggesting the promising potential for managing hypertension and type 2 diabetes through natural dietary intervention." (PMID 40427700, 2025). "Data on the use of angiotensin-converting enzyme (ACE) inhibitors and angiotensin receptor blockers (ARBs) were not available in the database, although both classes are recommended as first-line therapy in current hypertension guidelines." (PMID 41149285, 2025). "Although current antihypertensive drugs such as ACE inhibitors (ACEI), angiotensin receptor blockers (ARB), and beta-blockers can control BTKi-induced hypertension to some degree, the efficacy and safety of these medications still need to be further validated through large-scale clinical trials." (PMID 40453665, 2025). "Additionally, bioactive peptides have demonstrated the ability to inhibit angiotensin-converting enzyme (ACE), a key mechanism in controlling hypertension." (PMID 40871293, 2025). "We hypothesize that the protective effect of hypertension, diabetes, and CAD in AKI patients may be due to the widespread use of renoprotective medications in this group, including ACE inhibitors, ARBs, and SGLT2 inhibitors." (PMID 40807014, 2025).
Hypertension (continued). "Additionally, dipeptides that include valine or alanine have been shown to inhibit enzymes such as ACE, renin, and DPP IV, indicating their possible roles in managing hypertension and diabetes." (PMID 41585459, 2025). "Overall, ACE I/D genotypes and APOEε4 did not have a significant impact on brain volume in AD patients, regardless of hypertension status." (PMID 40372199, 2025). "In the treatment of arterial hypertension without other cardiovascular comorbidities, β-blockers are not considered first-line therapy; therefore, more appropriate medications, such as ACE inhibitors or sartans, were recommended." (PMID 40959457, 2025). "Past medical history included hypertension treated with an angiotensin-converting enzyme (ACE) inhibitor; there was no prior antiplatelet or statin therapy." (PMID 41357001, 2025). "Modern research has elucidated its multi-target mechanisms of action including antioxidant stress, angiotensin-converting enzyme (ACE) inhibition, endothelium-dependent vasorelaxation via nitric oxide synthase (NOS) activation, and mitigation of hypertension-induced renal damage." (PMID 40361727, 2025). "Additionally, antihypertensive therapy is critical for managing the increased prevalence of hypertension in HIV-positive individuals, with angiotensin-converting enzyme (ACE) inhibitors and calcium channel blockers being commonly used." (PMID 40787484, 2025). "DPP-IV-inhibitory peptides (e.g., LDQWLCEKL and VGINYWLAHK) suggest potential for type 2 diabetes management, while ACE inhibitors (such as YLGY and FFVAPFPEVFGK) could support cardiovascular health by reducing hypertension." (PMID 40077579, 2025). "The prevalence of hypertension and distribution of ACE gene genotypes did not significantly differ between men and women." (PMID 40370871, 2025). "ACE inhibitors and angiotensin receptor blockers are commonly used for hypertension, although they are not currently used as front-line therapies for AD and are under investigation for their potential neuroprotective and anti-inflammatory effects." (PMID 40699836, 2025). "In addition, tilianin inhibits angiotensin-converting enzyme (ACE), thereby preventing downstream vascular remodeling, fibrosis, and hypertension." (PMID 41254699, 2025). "In multivariable logistic regression analysis, changes in LVEF and WMSI were identified as significant predictors of MACE, along with prior revascularization, history of MI, diabetes mellitus, hypertension, age, imaging-guided PCI, beta-blocker therapy, ACE inhibitor therapy." (PMID 40438233, 2025). "It has been proposed that pharmacological intervention with appropriate antihypertensive agents, such as angiotensin-converting enzyme (ACE) inhibitors or angiotensin II receptor blockers (ARBs), may be beneficial for cancer patients experiencing hypertension." (PMID 40346640, 2025). "Docking simulations predict the preferred binding conformations and affinities of peptides within enzyme active sites or receptor pockets, commonly targeting ACE and dipeptidyl peptidase-IV (DPP-IV) due to their relevance in hypertension and diabetes management." (PMID 41226263, 2025). "Peptides can perform various biological activities based on their amino acid sequences, including angiotensin-converting enzyme (ACE) inhibitory, anti-hypertension, immune response modulation, blood clot prevention, anti-cancer, and antioxidant activities." (PMID 39483017, 2025). "The data on the inhibition of the angiotensin-converting enzyme (ACE) activity, acetylcholinesterase (AChE) activity, and advanced glycation endproduct (AGE) formation are important regarding hypertension, Alzheimer-type dementia, and diabetic complication, respectively." (PMID 40572519, 2025). "The results indicated that ACE genotypes, presence of apolipoprotein epsilon 4 (APOEε4), and brain volume did not significantly differ between patients with and without hypertension." (PMID 40372199, 2025).
Hypertension (continued). "Enalapril is the preferred ACE inhibitor in the Essential Drug List (EDL) of South Africa and hence the second most prescribed antihypertensive drug in patients attending a tertiary-level Hypertension Clinic at Groote Schuur Hospital, in South Africa." (PMID 40534840, 2025). "As expected, this ACE inhibitor, used to treat high blood pressure and congestive heart failure, did not present any activity in treating infection in G. mellonella caused by a S. aureus strain with increased efflux activity and strong biofilm production." (PMID 40001426, 2025). "However, the ACE/AngII/AT1 axis in hypertensive patients is overactivated, disrupting the balance between the ACE2/Ang1-7/mas axis and the ACE/AngII/AT1 axis, which further exacerbates the occurrence and development of hypertension and its complications." (PMID 39468572, 2024). "Consequently, inhibiting the activity of the ACE/Ang II/AT1R axis, achieved through the use of ACE inhibitors or ARBs, effectively reduces blood pressure and controls the development of hypertension." (PMID 39247619, 2024). "Consequently, this study affirms that cooked goat loin (70°C for 30) min, emerges as a source of bioactive peptides with ACE and DPP-IV inhibitory activities; these two bioactive properties correlated with preventing type 2 diabetes and hypertension." (PMID 38575133, 2024). "Two new ACE inhibitory peptides (HLHT and GWA) were isolated and purified from the meat protein hydrolysate of P. fucata, showing antihypertensive effects on rat hypertension." (PMID 39195461, 2024). "Upregulation of the ACE/Ang II/ATIR axis can elevate blood pressure, but excessive activation may induce aortic diseases such as hypertension, vascular dysfunction, atherosclerosis, and AA." (PMID 39247619, 2024). "In CKD patients without proteinuria and with hypertension, there is insufficient evidence that ACE inhibitors/ARBs improve CVD events and renal prognosis, regardless of the presence of DM complications." (PMID 38713253, 2024). "The patient, a 48-year-old Indian male with a longstanding history of well-controlled plaque psoriasis, presented with a significant flare-up of his skin condition shortly after the initiation of lisinopril, an angiotensin-converting enzyme (ACE) inhibitor, for hypertension management." (PMID 39364528, 2024). "Thus, the antihypertensive effect via the ACE inhibitory activity of a DPP4 inhibitory peptide is expected to be beneficial for the management of T2D patients with hypertension, as well as for hypertension patients with T2D." (PMID 39595018, 2024). "Although ACE inhibitors have been shown to reduce vascular inflammation, there is no convincing evidence indicating that ACE inhibitors reduce plasma levels of major inflammatory markers in hypertension models." (PMID 38891786, 2024). "Part of the vesicles released from endothelial cells also contain components of the RAS, especially ACE and ACE2, which might play a special role regarding the development of hypertension." (PMID 38397093, 2024). "These included age, gender distribution, body weight, prevalence of diabetes mellitus, hypertension, ischemic etiology, AF, LVEF, baseline BUN, serum creatinine, Na, K, NT‐proBNP levels, hemoglobin, and medication usage (ACE inhibitor or ARB, aldosterone antagonist, β‐blocker, and oral furosemide)." (PMID 39558518, 2024). "The only available randomized data on postoperative use of ACE inhibitors, applied for the sole purpose of reducing hematoma recurrence and not treatment of hypertension, was probably too small in size to yield meaningful results." (PMID 39200732, 2024). "Specifically, the yak milk ACE-inhibitory peptide KYIPIQ enhances nitric oxide (NO) synthesis and endothelial nitric oxide synthase (eNOS) expression in human vascular endothelial cells, potentially aiding in hypertension treatment and related conditions." (PMID 39201758, 2024).